MUC1 (mucin 1, cell surface associated)
Diseases named in the same sentence as MUC1 in open-access papers (continued):
Sharing a sentence is not in itself a finding about the gene and the disease.
dysplasia (3 papers, 2017 to 2022). A usually neoplastic transformation of the cell, associated with altered architectural tissue patterns. "The findings support the hypothesis that the epithelial colonization of spirochetes is significantly reduced by dysplasia likely due to loss of microvilli, and an increase of epithelial MUC1 expression might contribute to reduced spirochetal colonization in colonic mucosa." (PMID 35444914, 2022).
invasive lobular carcinoma (3 papers, 2010 to 2023). "In case 2, MUC1 was only positive in the individual tumor cells, which was significantly downregulated compared with the surrounding invasive lobular carcinoma." (PMID 37337182, 2023). "In summary, we presented a case of classical type invasive lobular carcinoma with abundant extracellular mucin production, cytoplasmic MUC1 expression and unequivocal HER2 gene amplification." (PMID 20550696, 2010).
kidney (3 papers, 2024 to 2025). "This article reviews the structural features, expression regulation mechanism, and research progress of MUC1 in the development of genitourinary cancers and its clinical applications." (PMID 39491020, 2024). "MUC1 is transiently elevated during acute kidney injury to promote recovery, but prolonged overexpression can lead to CKD." (PMID 38791999, 2024).
leiomyosarcoma (3 papers, 2015 to 2019). An uncommon, aggressive malignant smooth muscle neoplasm, usually occurring in post-menopausal women. "We examined the expressions of MUC1 and CD11c in primary and recurrent leiomyosarcoma (LMS) and liposarcoma (LPS) specimens." (PMID 31739284, 2019).
malignant meningioma (3 papers, 2015 to 2024). "In the GEO database, C1GALT1-specific chaperone (COSMC) and mucin 1 (MUC1) were significantly increased in malignant meningiomas (Grade II and III) compared with benign meningiomas (Grade I)." (PMID 38274327, 2024).
medullary cystic kidney disease type 1 (3 papers, 2014 to 2026). An inherited form of cystic kidney disease that leads to fibrosis and impaired renal function as a result of defects in the MUC1 gene, which encodes mucin 1. "Of note, pathogenic variants causing medullary cystic kidney disease type 1 may lie in a variable-number tandem repeat (VNTR) sequence in MUC1 and is missed by massively parallel sequencing." (PMID 34565340, 2021).
Miscarriage (3 papers, 2004 to 2018). A pregnancy that ends at a stage in which the fetus is incapable of surviving on its own, defined as the spontaneous loss of a fetus before the 22th week of pregnancy. "Significantly reduced expression of MUC1 can also affect the embryo selection function of endometrium, subsequently increasing the miscarriage rate or reducing the implantation rate." (PMID 23061681, 2012).
pancreatic disease (3 papers, 2014 to 2022). "A predictive model for identification of pancreatic disease was constructed using the U-indexes of MUC1, MUC2 and MUC4 based on quadratic or canonical discriminant analysis." (PMID 24714692, 2014).
rectal cancer (3 papers, 2019 to 2025). A primary or metastatic malignant neoplasm that affects the rectum. "A high level of MUC1 expression (positive vs. negative: OR = 0.79, 95% CI = 0.63–0.98, P = 0.03) was associated with rectum cancer." (PMID 31933627, 2019). "Our prior study of MUC1 and MUC2 in CRCs showed that MUC1 is an indicator of poor prognosis for Caucasian patients, but there is, for African American or Caucasian patients, no prognostic value for MUC2 when colon and rectal cancers along with MCAs and NMCAs are combined." (PMID 36916704, 2023).
salivary gland tumors (3 papers, 2015 to 2025). "Previous studies have analyzed the expression of Tn‐MUC1 in various cancers, but none have explored its roles in salivary gland tumors." (PMID 40844495, 2025).
signet ring cell carcinoma (3 papers, 2011 to 2014). A usually aggressive, poorly differentiated invasive adenocarcinoma characterized by the presence of malignant glandular cells in which the nucleus is pressed to one side by the presence of intracytoplasmic mucus. "Because enhancement of mucin secretion has been observed in signet ring carcinoma cells, behavior of MUC1, one of the mucins, has been examined." (PMID 22216327, 2011). "There are many immunohistochemical studies on MUC1 expression in GC, and most of them reported MUC1 staining in roughly more than 50% of both IGC and DGC except for signet-ring cell carcinoma, a poorly differentiated GC in which the MUC1 expression was observed only 10%." (PMID 24810688, 2014).
thymic carcinoma (3 papers, 2020 to 2023). Thymic carcinoma (TC) is a type of thymic epithelial neoplasm characterized by a high malignant potential. "Bcl-2, calretinin, CD5, CD117, CEA, GLUT1, IGF-1R, mesothelin, MOC31, MUC1, and p21 were higher expressed in thymic carcinomas." (PMID 35565429, 2022).
tubular adenoma (3 papers, 2010 to 2022). A usually polypoid neoplasm arising from the glandular epithelium. "Here, we report a case that showed abrupt abolition of mucosal surface fringe formation on a tubular adenoma (TA) and increased cytoplasmic MUC1 expression in the dysplastic epithelial cells compared with adjacent nondysplastic colonocytes." (PMID 35444914, 2022). "A total of 454 polyp specimens comprising 36 hyperplastic polyps, 15 serrated adenomas, 258 tubular adenomas, 114 tubulovillous adenomas, and 31 villous adenomas were included in this study, and were immunostained for MUC1, MUC2, MUC5AC and MUC6 by using mucin specific antibodies." (PMID 20929551, 2010). "Expression of colonic mucins (MUC1, MUC4, MUC17, MUC2, and MUC5AC) and O-glycans [Sialyl LewisA (CA19-9) and Tn/Sialyl-Tn on MUC1] were analyzed in HP (n=33), SSA/P (n=39), and tubular adenoma (TA) (n=36) samples by immunohistochemistry." (PMID 27705923, 2017).
Type 2 Diabetes (3 papers, 2022 to 2026). "Our results suggest that genetic variation in or near TAF3, MUC1/TRIM46, SHROOM3, and SLC22A7 are associated with the regulation of serum Mg2+ concentrations which may be partially explained by renal function, in type 2 diabetes." (PMID 38279093, 2024). "In conclusion, serum magnesium concentrations are associated with genetic variability around the regions of TAF3, MUC1/TRIM46, SHROOM3, and SLC22A7 in type 2 diabetes." (PMID 38279093, 2024).
Barrett esophagus (2 papers, 2017 to 2023). Esophageal lesion lined with columnar metaplastic epithelium which is flat or villiform. "Within the GSEA two groups of upper GI samples were compared; the comparison of non-dysplastic Barrett’s esophagus (NDBE) to normal esophageal squamous epithelium (Sq) gave 47 pathways that were enriched in NDBE compared to Sq, of which 28 were significant and of these 21% included MUC1." (PMID 28212575, 2017).
Chronic colitis (2 papers, 2022 to 2025). A chronic inflammatory disease of the large intestine (colon, cecum and rectum). "In both groups with chronic colitis, a decrease in the transmembrane mucin Muc1 mRNA expression in the colon was observed." (PMID 40863977, 2025). "Interestingly, the levels of Muc1 and Muc2 increased significantly during remission of chronic colitis, indicating that the synthesis of epithelial mucin was activated during remission." (PMID 36176029, 2022).
chronic hepatitis (2 papers, 2014 to 2019). An active inflammatory process affecting the liver for more than six months. "In studies of mucin expression in various hepatobiliary diseases, MUC1 was expressed in different frequency in all types of pathological lesions, especially in cases of destructive cholangitis in PBC and hepatic duct injuries in chronic hepatitis." (PMID 30875782, 2019).
chronic rhinosinusitis (2 papers, 2018 to 2025). Chronic form of sinusitis. "Recent data indicate that MUC1 cytoplasmic tail (CT) membrane mucin can mediate corticosteroid efficacy in chronic rhinosinusitis." (PMID 30458870, 2018).
clear cell ovarian carcinomas (2 papers, 2020 to 2021). "We first established ovarian clear cell carcinoma cell lines overexpressing MUC1 with sialylated glycans by transfecting MUC1 cDNA into ES-2 cells." (PMID 34641504, 2021). "We developed a method to quantify adhesion of ovarian clear cell carcinoma cells to mesothelial cells and to assess how surface expression of MUC1 with sialylated glycans affects this adhesion." (PMID 34641504, 2021).
colorectal polyps (2 papers, 2010 to 2017). "Given these analyses, beside the expression status of MUC1, left sidedness of colorectal polyps corresponded to increased risk of invasion to mucosa and muscularis mucosae, having high configuration and polyp grading." (PMID 20929551, 2010). "Ordinal regression analysis demonstrated a positive association between the level of staining for MUC1 and risk of being of high configuration/grade in colorectal polyps." (PMID 20929551, 2010). "But based upon these models, one can confidently argue about the potential applicability of MUC1 expression as a predictor of malignant transformation, and invasive behavior of colorectal polyps." (PMID 20929551, 2010). "Almost all of mucins that are studied here can provide predictions on the invasive behavior of colorectal polyps; however, only MUC1 can provide such information in respect to both the grading and configuration of colorectal polyps." (PMID 20929551, 2010). "Level of expression of MUC1 and 5 was associated with the level of configuration, and level of expression of MUC 1 and 2 could provide predictions on grading of colorectal polyps." (PMID 20929551, 2010). "Thus, MUC1 is the most reliable predictor of malignant transformation of colorectal polyps among the mucins that are studies in this article." (PMID 20929551, 2010). "MUC1, MUC2, MUC5AC, and MUC6 have the potential to be used as predictors of malignant transformation and invasion to mucosa or the muscularis mucosae in colorectal polyps." (PMID 20929551, 2010). "The aim of the present study was to determine the pattern of expression of MUC1, MUC2, MUC5AC and MUC6 in colorectal polyps and to evaluate the applicability of using mucin expression in predicting the extent of malignant transformation in colorectal polyps." (PMID 20929551, 2010). "Binary logistic regression analysis indicated that positive staining for MUC1, and MUC6, and negative staining for MUC2 would increase the risk of invasion to mucosa or the muscularis mucosae in colorectal polyps." (PMID 20929551, 2010).
conjunctivitis (2 papers, 2017 to 2020). Inflammation of the conjunctiva of the eye. "In another study, MUC1 suppressed conjunctivitis in mice caused by Staphylococcus and Streptococcus species." (PMID 28588132, 2017).
duodenal adenocarcinoma (2 papers, 2019 to 2020). A carcinoma that arises from glandular epithelial cells of the duodenum. "A similar relationship between MUC1 expression and aggressive tumor is also reported in duodenal adenocarcinoma and esophageal adenocarcinoma." (PMID 32662743, 2020).
endometrioid tumor (2 papers, 2014 to 2025). A benign, borderline, or malignant epithelial tumor of the female reproductive system characterized by the presence of glands and/or cysts lined by neoplastic cells that resemble endometrial cells. "For MUC1 SNP, rs4072037, women homozygous for the G variant had a non-significantly decreased risk for serous invasive types but elevated risk for serous borderline tumors, mucinous borderline and invasive tumors, and endometrioid tumors." (PMID 24551091, 2014). "The two endometrioid tumor models, MPOSE and MPOSE-AdCre, are MUC1 high." (PMID 40642792, 2025).
endometritis (2 papers, 2021 to 2022). An acute or chronic, usually bacterial infectious process affecting the endometrium. "Similarly, expression of MUC1 was lower in endometrium of cows without subclinical endometritis compared with those that had subclinical endometritis." (PMID 35204175, 2022). "Similarly, expressions of IFNT, ISG15, CXCL10, PPARG, RXRG, SLC2A1, and SLC27A6 proteins were greater and MUC1 was lower in the endometrium of cows without endometritis compared with cows with endometritis (p < 0.05)." (PMID 33920430, 2021).
eosinophilia (2 papers, 2025). "Since eosinophil is a widely recognized biomarker of disease severity, the correlation between MUC1 and eosinophilia suggests that MUC1 should also be considered a potential marker of CRSwNP severity." (PMID 41295249, 2025). "Moreover, the imbalance between IL-22 and IL-22R1 expression could influence local eosinophilia and disease severity through modulation of MUC1-dependent mechanisms." (PMID 41295249, 2025).
epithelial ovarian tumors (2 papers, 2014 to 2019). "In general, all histologic types of epithelial ovarian tumors, both benign and malignant, express MUC1 on the cell surface by immunohistochemistry." (PMID 24551091, 2014).
Erythema (2 papers, 2024). Redness of the skin, caused by hyperemia of the capillaries in the lower layers of the skin. "A previous report indicated that erythema at the vaccination site (30 mm in longitudinal diameter or more) is associated with induction of antitumor immunity and clinical benefits from the WT1/MUC1-DC vaccine." (PMID 38336778, 2024).
esophageal adenocarcinoma (2 papers, 2017 to 2020). A malignant tumor with glandular differentiation arising predominantly from Barrett mucosa in the lower third of the esophagus. "We investigate MUC1 as a therapeutic target in Barrett’s epithelium (BE) and esophageal adenocarcinoma (EA) and provide proof of concept for a light based therapy targeting MUC1." (PMID 28212575, 2017). "Four antibodies against different epitopes of MUC1 were used to stain patient samples representing various stages toward progression to cancer; Sq epithelium, NDBE, low-grade dysplasia (LGD), high grade dysplasia (HGD) and invasive esophageal adenocarcinoma (EA)." (PMID 28212575, 2017).
gallbladder adenocarcinoma (2 papers, 2021 to 2024). A carcinoma that arises from glandular epithelial cells of the gall bladder. "Specifically, MUC1 expression exhibits a significant elevation in gallbladder adenocarcinoma compared to chronic cholecystitis, while MUC5AC expression tends to diminish in neoplastic conditions relative to chronic inflammation." (PMID 38786750, 2024). "Implications regarding mucin types, particularly MUC1 and MUC5AC, have emerged in the context of malignant tumor development, impacting the biological characteristics and advancement of gallbladder adenocarcinoma." (PMID 38786750, 2024).
gallstones (2 papers, 2022 to 2025). Solid crystalline precipitates in the biliary tract, usually formed in the gallbladder, resulting in the condition of cholelithiasis. "While earlier studies have demonstrated that RBL1‐T369 phosphorylation releases E2F transcription factors, we found that phosphorylation at this site also releases Sp1, allowing it to drive MUC1 transcription during gallstone formation." (PMID 39932450, 2025). "Additionally, previous studies and our results indicate that epithelial MUC1 seems to play a key role in the up‐regulation of the gel‐forming MUC5ac during cholesterol gallstone formation." (PMID 39932450, 2025). "Additionally, we uncovered the gallbladder FXR‐miR30c/e‐SDPR axis as a novel mechanism linking caveolae disruption, nuclear PKCζ‐RBL1‐Sp1 signaling and MUC1‐regulated gallstone formation." (PMID 39932450, 2025). "The increase of MUC1 mucin in the gallbladder epithelium can promote the absorption of cholesterol in mice and inhibit the movement of the gallbladder, thereby promoting the formation of gallstones found MUC1 and MUC2 gene loci significantly associated with gallstones in Chinese males." (PMID 35651949, 2022). "Together with ceramide‐activated PKCζ nuclear translocation and RBL1‐Sp1 activation, this induces MUC1·5ac hyperproduction, which combines with high CSI to promote gallstone formation." (PMID 39932450, 2025). "Studies have shown that oral pathogenic bacteria affect gallbladder movement and the expression of mucin genes (MUC1, MUC3, and MUC4) through the immune regulation mechanism, regulate cholesterol metabolism and promote the formation of gallstone." (PMID 35651949, 2022).
gastrointestinal carcinomas (2 papers, 2015 to 2023). "Emerging evidence provides support for the oncogenic role of MUC1 in gastrointestinal carcinomas and relates its expression to an invasive phenotype." (PMID 26436698, 2015). "MUC1, MUC2 and MUC5AC are more significant than any other mucins for the differential diagnosis of PMOC and MMOC, particularly in gastrointestinal carcinomas." (PMID 37664708, 2023). "MUC1, MUC2 and MUC5AC are dominant in MOC and can be used in the differential diagnosis of PMOC and MMOC, particularly in gastrointestinal carcinomas." (PMID 37664708, 2023).
Hepatic cysts (2 papers, 2019 to 2021). "Analysis of different glycoforms of MUC1 in various cystic liver diseases allowed for suggestions concerning cystogenesis in the liver, from IBDs through biliary microhamartomas, to hepatic cysts." (PMID 30875782, 2019). "The highly-glycosylated glycoform of MUC1 (“mature” form) present in ~half of hepatic cysts studied, may be related to the late cystogenetic process in liver cystogenesis." (PMID 30875782, 2019).
HIV-1 infection (2 papers, 2022). The type species of lentivirus and the etiologic agent of acquired immunodeficiency syndrome (AIDS). "Milk exosomes were shown to express soluble mucin 1 (MUC1) and incubation of monocyte-derived dendritic cells (MDDCs) with exosomes was observed to protect against HIV-1 infection in vitro." (PMID 35406056, 2022).
Hypertension (2 papers, 2021 to 2023). The presence of chronic increased pressure in the systemic arterial system. "Moreover, ADTKD-MUC1 with the MUC1 mutation was found to be associated with ESRD and hypertension." (PMID 34638981, 2021).
Insulin resistance (2 papers, 2019 to 2022). Increased resistance towards insulin, that is, diminished effectiveness of insulin in reducing blood glucose levels. "Tumor protein D52-like 1 (TPD52L1), OLFML1, and MUC1 are novel biomarkers for the development of insulin resistance." (PMID 30678306, 2019).
intestinal-type carcinoma (2 papers, 2010 to 2016). "In accordance with the Lauren classification, the expression rate of MUC1 in intestinal-type carcinomas was significantly higher than that in diffuse-type carcinomas (pooled OR = 1.76, 95% CI: 1.27–2.44, P = 0.0008 fixed-effect)." (PMID 27190429, 2016). "The histological classification indicated that CK20 had high sensitivity (100%) for intestinal-type carcinoma and that MUC1 had high sensitivity (94%) for pancreatobiliary-type carcinoma, and both correlations were significant (p < 0.001 and p < 0.001, respectively)." (PMID 21106111, 2010).
mastitis (2 papers, 2017 to 2025). Inflammation of breast tissue during lactation or postpartum due to an obstructed duct or infection. "In the ceRNA network examined in this study, MUC1 is associated with mastitis resistance and milk fat synthesis." (PMID 39795032, 2025). "The expression of MUC1 was significantly affected by mastitis treatment, with a lower expression in mastitis-treated goats at 1 d after IMI, and a larger expression in TZD-treated versus control goats at 7 d after IMI." (PMID 28740504, 2017).
MRKH syndrome (2 papers, 2015 to 2021). "We then focused our attention on the expression of other genes selected from the literature which are likely to play a role in MRKH syndrome phenotype determination: MUC1, HOXC8 and GREB1L." (PMID 34063745, 2021). "Recently, a valuable gene expression profile of in vitro cultured vaginal tissue from MRKH syndrome patients has identified dysregulation of MUC1, WNT7A, JAG1 and DLL1, emphasizing the critical role of canonical Wnt signaling and the NOTCH pathway." (PMID 26075712, 2015). "In order to establish a correlation between MRKH syndrome phenotype and gene expression pattern, we performed PCA on data from RT-qPCRs for PRKX, MUC1, HOXC8 and GREB1L loci." (PMID 34063745, 2021).